RPSA (ribosomal protein SA)
Description:
Required for the assembly and/or stability of the 40S ribosomal subunit. Required for the processing of the 20S rRNA-precursor to mature 18S rRNA in a late step of the maturation of 40S ribosomal subunits. Also functions as a cell surface receptor for laminin. Plays a role in cell adhesion to the basement membrane and in the consequent activation of signaling transduction pathways. May play a role in cell fate determination and tissue morphogenesis. Acts as a PPP1R16B-dependent substrate of PPP1CA. (Microbial infection) Acts as a receptor for the Adeno-associated viruses 2,3,8 and 9. (Microbial infection) Acts as a receptor for the Dengue virus. (Microbial infection) Acts as a receptor for the Sindbis virus. (Microbial infection) Acts as a receptor for the Venezuelan equine encephalitis virus. (Microbial infection) Acts as a receptor for the pathogenic prion protein. (Microbial infection) Acts as a receptor for bacteria.
Synonyms: 37LRP; LRP/LR; 67LR; LamR; LBP/p40; LAMBR; LAMR1; LRP; p40; SA; uS2; ICAS; LBP; NEM/1CHD4
Tractability: Small molecule: an approved drug acts on it; a structure with a bound ligand is known; a high-quality ligand is known. Antibody: its Gene Ontology location is reachable by antibodies, with high confidence; UniProt places it where antibodies can reach, with medium confidence; the Human Protein Atlas places it where antibodies can reach. PROTAC: UniProt records ubiquitination sites on it; ubiquitination databases record sites on it; its protein half-life has been measured; a small molecule that binds it is known. Other modalities: a drug acting on it is in phase 2 or 3 trials.
Target class: Other cytosolic protein
Gene: Protein-coding gene on chromosome 3 (39,406,709 to 39,426,255, forward strand). Ensembl gene ENSG00000168028.
Subcellular location: Cell membrane; Cytoplasm; Nucleus
Subcellular location (Human Protein Atlas): Cytosol; Plasma membrane
Pathways (Reactome):
Metabolism of proteins: Eukaryotic Translation Termination; Formation of a pool of free 40S subunits; Formation of the ternary complex, and subsequently, the 43S complex; GTP hydrolysis and joining of the 60S ribosomal subunit; L13a-mediated translational silencing of Ceruloplasmin expression; PELO:HBS1L and ABCE1 dissociate a ribosome on a non-stop mRNA; Peptide chain elongation; Ribosomal scanning and start codon recognition; SRP-dependent cotranslational protein targeting to membrane; Translation initiation complex formation; ZNF598 and the Ribosome-associated Quality Trigger (RQT) complex dissociate a ribosome stalled on a no-go mRNA
Disease: Dengue Virus Attachment and Entry; SARS-CoV-1 modulates host translation machinery; SARS-CoV-2 modulates host translation machinery; Viral mRNA Translation
Metabolism of RNA: Major pathway of rRNA processing in the nucleolus and cytosol; Nonsense Mediated Decay (NMD) enhanced by the Exon Junction Complex (EJC); Nonsense Mediated Decay (NMD) independent of the Exon Junction Complex (EJC)
Cellular responses to stimuli: Response of EIF2AK4 (GCN2) to amino acid deficiency
Developmental Biology: Regulation of expression of SLITs and ROBOs
Metabolism: Selenocysteine synthesis
Gene Ontology:
Molecular function: DNA binding; protein binding; ribosome binding; RNA binding; structural constituent of ribosome; laminin binding; laminin receptor activity
Biological process: antiviral innate immune response; cytoplasmic translation; ribosomal small subunit assembly; translation; cell adhesion
Cellular component: cytoplasm; cytosol; cytosolic ribosome; cytosolic small ribosomal subunit; extracellular exosome; membrane; nucleus; plasma membrane; nucleoplasm; ribosome; small ribosomal subunit
Genetic constraint (gnomAD): Loss-of-function variants: 0 observed, 20.79 expected, observed/expected ratio (o/e) 0, 90% interval 0 to 0.14. The upper end of that interval is the gene's LOEUF score, 0.14, which puts it in group 1 of 6, group 1 being the genes least tolerant of losing a copy. Missense variants: 105 observed, 249.23 expected, observed/expected ratio (o/e) 0.42, 90% interval 0.36 to 0.5. Synonymous variants: 77 observed, 86.61 expected, observed/expected ratio (o/e) 0.89, 90% interval 0.74 to 1.08.
Homologues: Orthologues: macaque RPSA (99% identical), mouse Rpsa (99% identical), guinea pig RPSA (99% identical), tropical clawed frog rpsa (93% identical), zebrafish rpsa (92% identical), dog RPSA (91% identical), Drosophila melanogaster sta (56% identical), Caenorhabditis elegans rps-0 (53% identical). Paralogues in human: RPSA2 (99% identical).
Diseases named in the same sentence as RPSA in open-access papers:
RPSA is named in the same sentence as 63 diseases in open-access papers, as found by Europe PMC text mining. Sharing a sentence is not in itself a finding about the gene and the disease. The quoted sentences say what the papers report.
pancreatic cancer (10 papers, 2020 to 2025). "It is reported that RPSA is highly expressed in the invasive human pancreatic cancer cell line PC-1.0 and is linked to Integrin α 6 (ITGA6), a protein involved in the regulation of cell–cell attachment." (PMID 34873618, 2021). "On the other hand, inhibition of RPSA leads to a reduction of p-ERK1/2 levels in pancreatic cancer cells." (PMID 40736249, 2025). "From a mechanistic point of view, proteomic analysis performed in pancreatic cancer cells, revealed that RPSA interacted with Integrin alpha 6 (ITGA6) and that they colocalized on the plasma membrane as showed by immunofluorescence analysis." (PMID 37452879, 2023). "SiRNA mediated RPSA knock-down resulted in a significant decrease of viability in different cancer cell lines, such as BC and oesophageal cancer cells, pancreatic cancer and neuroblastoma cells, melanoma and CRC cells." (PMID 37452879, 2023). "RPSA was also found to promote pancreatic cancer invasion and metastasis through the MAPK signaling pathway." (PMID 36293493, 2022). "Another report further proved that RPSA regulates pancreatic cancer mainly through inhibiting caspase activity, which is a key protein of mediating apoptosis." (PMID 33635875, 2021). "For instance, ITGA6 synergistically interacted with RPSA to promote cell migration and invasion in pancreatic cancer." (PMID 33317527, 2020). "Taken together, our data suggest that TRPM7/RPSA complex regulated human pancreatic cancer cell migration." (PMID 32733880, 2020). "Furthermore, TRPM7 and RPSA co-localized at the plasma membrane in human pancreatic cancer cells, and this complex was proposed to regulate cell migration." (PMID 38255793, 2024). "RPSA has also been reported to evade apoptosis by impeding caspase activity in pancreatic cancer." (PMID 36293493, 2022). "Therefore, highly expressed RPSA in pancreatic cancer is reported to be closely related to the cancer invasion and metastasis due to the binding of RPSA-mediated cell adhesion laminin, further revealing a poor prognosis." (PMID 33635875, 2021). "Knockdown of RPSA and ITGA-6 inhibits these pathways and leads to a reduction in pancreatic cancer cell line invasion and metastasis." (PMID 34873618, 2021). "ITGA6 promotes the activation of PI3K after regulating the phosphorylation level of AKT, while RPSA activates MAPK signaling pathway which consequently stimulates the invasion and the metastasis of pancreatic cancer cells." (PMID 34873618, 2021). "For this reason, MIA PaCa-2 pancreatic cancer cells were pre-incubated with EGCG (10 μM) for 1 h, then incubated with or without AG-9 (10–7 M) for 24 h before fixation with paraformaldehyde and labeling with anti-TRPM7 and RPSA antibodies." (PMID 32733880, 2020). "Moreover, our results confirm that RPSA is overexpressed in human pancreatic tumor tissues compared to their adjacent non-tumor counterparts." (PMID 32733880, 2020).
asplenia (9 papers, 2018 to 2024). "RPSA mutations also lead to congenital asplenia, illustrating the role of RPSA in tissue differentiation." (PMID 38114488, 2023). "We would like to present the diagnostic journey for a child with asplenia and haploinsufficiency of the RPSA gene coexisting with SLC25A38, SNORA6, SNORA62 and MOBP gene deletion." (PMID 34781974, 2021). "In four families, mutations in the RPSA gene were found, a gene previously linked to congenital asplenia." (PMID 31498527, 2020). "Previous work showed that RPSA mutations cause congenital asplenia with variable penetrance in humans." (PMID 31498527, 2020). "The families with RPSA variants (Families 1–4) all had a combination of asplenia and intestinal varices." (PMID 31498527, 2020). "There are mutations found in the LAMR/RPSA gene which can be linked to congenital asplenia, a dysfunction of the spleen." (PMID 30577491, 2018). "Recently, haploinsufficiency for the RPSA gene encoding ribosomal protein SA was identified as one factor associated with isolated congenital asplenia." (PMID 30105023, 2018). "Copy number variations in RPSA gene locus are ultrarare cause of isolated asplenia." (PMID 34781974, 2021). "As exemplified by variants in untranslated RPSA exons with predicted functional impact comparable to fully penetrant variants but incomplete penetrance in the context of isolated congenital asplenia, the phenotypic penetrance may be modulated by various additional mechanisms." (PMID 37761828, 2023). "This included genes associated with asplenia i.e. GJA1, HMOX1, RPSA, STIM1 and AIRE." (PMID 34781974, 2021). "GJA1, HMOX1 and RPSA, have been described as defective in isolated congenital asplenia." (PMID 34781974, 2021). "Next generation sequencing for the ribosomal protein SA (RPSA) gene associated with isolated anatomic asplenia was obtained, but did not demonstrate any mutations." (PMID 31703560, 2019). "This confirms the diagnosis of Congenital Isolated Asplenia (ICAS, OMIM # 271400) resulting from de novo occurring monoallelic deletion of the RPSA gene." (PMID 34781974, 2021).
lung carcinoma (9 papers, 2012 to 2023). "For instance, in A549 lung cancer cell line, downregulation of RPSA with specific siRNA, inhibited cellular migration activity, as evaluated by scratch motility assay." (PMID 37452879, 2023). "Reversely, siRNA-mediated RPSA knock-down impeded telomerase activity in breast and lung cancer cells." (PMID 37452879, 2023). "RPSA is also reported to be highly expressed in lung cancer, colorectal cancer, breast cancer and esophageal cancer, and RPSA can prevent tumor cells from autophagy in both breast cancer and esophageal cancer." (PMID 33635875, 2021). "As for the six candidate cancer subtypes and healthy controls in our study, RPSA can distinguish colorectal cancer and lung cancer from the other subtypes." (PMID 29152097, 2017). "Thus, a scratch motility assay was performed after RPSA siRNA transfection to determine whether LRP downregulation would affect the migration potential of the A549 lung cancer cells." (PMID 36579897, 2023). "Through q-RT-PCR analysis, we found six genes (DDR1, HSP90B1, SDC1, RPSA, ERGIC3, and LPCAT1) significantly up-regulated and two genes (GPX3 and TIMP3) significantly down-regulated in the lung cancer tissues." (PMID 23374247, 2013). "The down-regulated RPSA, RPL9, TMSB4X and TUBA1B in normal lung (DDD1) were significantly up-regulated in lung cancer (DDD2)." (PMID 23122428, 2012). "The ribosomal protein SA, that functions as the lamin receptor in cell adhesion of the basement membrane, was reported to be up-regulated in NSCLC as evidenced by suppression subtractive hybridization of cDNA libraries generated from lung cancer patients." (PMID 27602772, 2016).
breast carcinoma (8 papers, 2017 to 2023). "Ribosomal protein SA (RPSA) has the potential to interfere with autophagy in breast cancer and esophageal tumor cells." (PMID 37444576, 2023). "Here, we found four upregulated hub genes (RPSA, SEC61A1, ITGB1, PSMB5) and three downregulated hub genes (PSME3, SNRNP70, SRSF3) that are significantly associated with poor overall survival of breast cancer patients." (PMID 36293493, 2022). "Numerous studies have elucidated that RPSA plays a pivotal role in tumorigenesis and cancer progression in breast cancer, esophageal cancer, Alzheimer's disease, colorectal cancer, and malignant melanoma." (PMID 32964027, 2020). "We identify RPSA, RPS5, RPS20, RPL5, RPL11 and RPL23A as six interesting cancer driver candidates and show a tumor suppressor role for RPL5 in the context of breast cancer." (PMID 28147343, 2017).
prion disease (7 papers, 2010 to 2023). A transmissible disease that is caused by a protein that is able to induce abnormal folding of normal cellular proteins, leading to characteristic spongiform brain changes, which are associated with neuronal loss without an inflammatory response. "Further genetic studies on whether variants in RPSA gene are associated with human prion disease should examine various ethnicities and larger numbers." (PMID 21838916, 2011). "In the context of prion disease, RPSA is needed for the internalization and propagation of prion proteins." (PMID 20233419, 2010). "The ribosomal protein SA (RPSA), previously named 37-kDa laminin receptor precursor/67-kDa laminin receptor (LRP/LR) is a multifunctional protein that plays a role in a number of pathological processes, such as cancer and prion diseases." (PMID 20233419, 2010). "The second, RPSA, is surface ribosomal protein that interacts with laminins (LAM), a dual-specificity phosphatase 18 (DUSP18), and prion protein 2 (PRND), which taken together may suggest various pathological processes such as prion diseases and cancer." (PMID 32624006, 2020).
viral infection (6 papers, 2020 to 2025). "In the future, it will be interesting to investigate whether all these functions of RPSA are interconnected and to investigate the underlying mechanism in viral infection and propagation." (PMID 40510596, 2025). "However, the role and underlying mechanisms of RPSA in virus infection and inflammation remain unclear." (PMID 38114488, 2023). "Given the high conservation of RPSA, our discovery provides a new target for further research on how lipid metabolism can be influenced to limit viral infection." (PMID 40736249, 2025). "Given the role of RPSA as a receptor in various viral infections, we focused on it for further research and systematically studied the possible conservative mechanism of RPSA in porcine enteric coronavirus replication." (PMID 40736249, 2025). "Taken together, we have revealed the function and the mechanism of RPSA in the host response to viral infection." (PMID 38114488, 2023). "Taken together, nuclear sensor RPSA is essential for host defense against nuclear-replicating virus infection in vivo." (PMID 38114488, 2023). "Here, we identified nuclear RPSA as an innate sensor that promotes the host’s innate inflammatory response against virus infection." (PMID 38114488, 2023). "To evaluate the physiological importance of RPSA in the host defense against nuclear-replicating virus infection, we first infected Rpsafl/flLyz-Cre+ mice and littermates with HSV-1." (PMID 38114488, 2023). "In this study, we find that the nuclear RPSA interacts with the NF-κB P65 subunit after virus infection and participates in promoting the transcription of proinflammatory cytokine genes." (PMID 38114488, 2023). "To clarify the function of RPSA in the innate response against viral infection, we disturbed the endogenous Rpsa expression in multiple cell types." (PMID 38114488, 2023). "RPSA also plays a role in regulating the mitogen-activated protein kinase (MAPK) signaling pathway, and many viral infections have been associated with deviations from well-balanced control of the MAPK signaling cascade, such as Ebola virus and influenza A virus." (PMID 37007947, 2023). "Taken together, our data have demonstrated that RPSA, sensing nucleic acids in the host nucleus, then selectively promotes the proinflammatory cytokine gene transcription through epigenetically remolding chromosome accessibility in response to viral infection." (PMID 38114488, 2023). "The screening revealed that knocking down Rpsa robustly repressed HSV-1-induced expression of Il1b, the typical anti-viral cytokine, as well as a set of proinflammatory cytokines genes, suggesting RPSA as an important molecule in virus infection-triggered innate inflammatory response." (PMID 38114488, 2023). "In this study, we demonstrated that RPSA resists viral infection by selectively promoting proinflammatory cytokines expression, where we put forward a hypothesis that RPSA may synergize with other innate sensors to fight the virus." (PMID 38114488, 2023). "Here, we showed that FMDV VP1 interacted with host RPSA in the context of viral infection." (PMID 31694957, 2020). "RPSA clearly pulled down FMDV VP1 protein in the context of viral infection." (PMID 31694957, 2020). "Since activation of the MAPK signaling pathway by virus infection leads to the expression of proinflammatory cytokines and chemokines, we next evaluated the expression of these factors in PEDV-infected WT and RPSA-KO cells." (PMID 40736249, 2025).
colorectal cancer (5 papers, 2017 to 2024). A primary or metastatic malignant neoplasm that affects the colon or rectum. "In colorectal cancer cells, anti-RPSA antibody detected both the 67 and the 42-kDa RPSA immunoreactive components in the digitonin-generated cytosolic fractions (lanes 2) as well as in the Triton X-100-generated membrane fractions (lanes 3)." (PMID 38606907, 2024). "There is a significant change in the proteome of late-stage colorectal cancer cells when transfected with Human-RPSA siRNA." (PMID 33836696, 2021). "Western blot analyses of the 67LR were done using a panel of commercially available anti-67LR antibodies, all derived from RPSA peptides, on total protein lysates prepared from Caco-2/15 and SW620 colorectal cancer cells under reduced and denatured conditions." (PMID 38606907, 2024).
tuberculosis (5 papers, 2019 to 2024). A chronic, recurrent infection caused by the bacterium Mycobacterium tuberculosis. "Mutations in rpsA is linked to pyrazinamide resistance, a drug used for treatment of tuberculosis, and it has also been shown to mutate in bacteria stressed with various chemicals." (PMID 38958463, 2024). "We identified a set of 60 SNVs associated with extensively drug-resistant tuberculosis (XDR-TB), among which 42 SNVs were non-synonymous mutations located in the coding regions of nine key genes (ctpI, desA3, mce1R, moeB1, ndhA, PE_PGRS4, PPE18, rpsA, secF)." (PMID 38745294, 2024). "In addition, we found no Rv2783c mutations in 42 PZA-susceptible extensively drug-resistant tuberculosis (XDR-TB) clinical isolates without pncA and rpsA mutations." (PMID 31718097, 2019).
Alzheimer disease (4 papers, 2019 to 2025). A progressive, neurodegenerative disease characterized by loss of function and death of nerve cells in several areas of the brain leading to loss of cognitive function such as memory and language. "The KEGG pathway analysis of differential peaks showed that the loss of RPSA reduced the expression of many genes involved in inflammatory diseases like rheumatoid arthritis and Alzheimer’s disease." (PMID 38114488, 2023).